RNY4P29 (RNY4 pseudogene 29)
Gene: Miscellaneous RNA gene on chromosome 13 (58,527,655 to 58,527,751, reverse strand). Ensembl gene ENSG00000222733.
Homologues: Orthologues: chimpanzee Y_RNA (100% identical). Paralogues in human: RNY4P30 (96% identical), RNY4P9 (93% identical), Y_RNA (86% identical), RNY4 (85% identical), RNY4P6 (85% identical), Y_RNA (84% identical), RNY4P19 (82% identical), Y_RNA (82% identical), RNY4P13 (81% identical), RNY4P7 (81% identical), RNY4P10 (80% identical), RNY4P14 (80% identical), and 87 more.